TYK2 (tyrosine kinase 2)
Diseases named in the same sentence as TYK2 in open-access papers (continued):
Sharing a sentence is not in itself a finding about the gene and the disease.
Immunodeficiency (28 papers, 2010 to 2025). Failure of the immune system to protect the body adequately from infection, due to the absence or insufficiency of some component process or substance. "Laboratory investigations frequently reveal normal quantities of immune cells but impaired cellular signaling responses, distinguishing TYK2 deficiency from combined immunodeficiencies characterized by lymphopenia." (PMID 41465118, 2025). "Autosomal recessive, complete TYK2 deficiency leads to immunodeficiency, while variants that reduce TYK2 signalling, including TYK2:p.Pro1104Ala, are associated with protection from autoimmunity." (PMID 39835539, 2025). "We present a pediatric case from Kazakhstan to broaden the clinical and molecular spectrum of TYK2-related immunodeficiency and accentuate diagnostic challenges." (PMID 41465118, 2025). "Inborn immune deficiencies, such as the one in tyrosine kinase 2 (TYK2), a Janus kinase associated with several cytokine receptors, have sparked particular interest in recent years." (PMID 38365982, 2024). "The TYK2 locus is associated with ten different immune disorders, with three independent signals reported." (PMID 35618845, 2022). "For example, mutations in IL2RA and IL7R cause immunodeficiency and mutation in TYK2 and STAT3 have been reported to cause hyper-IgE syndrome." (PMID 21552549, 2011). "Although the precise immunophenotype of TYK2 deficiency varies, most affected individuals exhibit normal lymphocyte counts but aberrant cytokine responses, distinguishing this condition from combined immunodeficiencies." (PMID 41465118, 2025). "Nevertheless, we must bear in mind that completely inhibiting TYK2 may be counterproductive, as it might lead to susceptibility to microorganisms (e.g., mycobacteria and virus) and immunodeficiency." (PMID 37854597, 2023). "Patients carrying TYK2 loss-of-function mutations are usually characterized by immunodeficiency, which may increase the risk of health outcomes such as cancer." (PMID 36842216, 2023). "Genes with fine-mapped coding variants, such as NOD2 and TYK2, are also historically known to be responsible for Blau syndrome (dominant) and immunodeficiency (recessive) respectively, suggesting converging biological mechanisms between polygenic and Mendelian immune disorders." (PMID 35041074, 2022). "However, germline inactivation of TYK2 is associated with auto-immune and immunodeficiency diseases and patients with TYK2 deficiency have bacterial, viral, and fungal infections, highlighting its biological importance." (PMID 33672930, 2021). "Despite the reduced T-cell activation response, individuals carrying rs34536443 protective alleles do not have an increased risk for infections or an otherwise impaired immune system, whereas individuals with complete TYK2 loss of function develop immunodeficiency." (PMID 33293539, 2020). "However, reports on human TYK2 deficiency show a less severe immunodeficiency phenotype compared to JAK3 deficiency." (PMID 30353145, 2018). "For example, inactivating mutations in JAK3 can cause severe combined immunodeficiency (SCID), while loss-of-function mutations in TYK2 result in milder immunodeficiency." (PMID 40264772, 2025). "The remained TYK2 signal is low enough to allow protection against autoimmunity but still sufficient to prevent detrimental immunodeficiency." (PMID 35693820, 2022). "STAT3 and TYK2 signaling alterations are associated with Hyper IgE syndrome (HIES), a rare immunodeficiency characterized by elevated serum immunoglobulin E (IgE), skin inflammation, and recurrent skin and lung infections." (PMID 34439323, 2021). "The important role of TYK2 in immune-surveillance is also in line with findings in patients who carry mutated TYK2 alleles which lead to loss of TYK2, lowered TYK2 levels, or expression of kinase-inactive TYK2, and that show primarily immunodeficiencies." (PMID 31694222, 2019).
Immunodeficiency (continued). "Their findings can support further the role of TYK2 targeting as the possible promising treatment for these auto-immune diseases." (PMID 31057722, 2019). "Initially, cancer research focused on JAK1-3, while the TYK2 impact on disease was predominantly studied in inflammatory and (auto-)immune diseases." (PMID 31694222, 2019). "The fundamental role of TYK2 in autoimmunity and immunodeficiencies is well‐established." (PMID 39835539, 2025). "TYK2 deficiency, often via LOF mutations, is frequently involved in severe immunodeficiency." (PMID 34439323, 2021). "All this evidences indicate that rs34536443*C may allow a sufficient TYK2-mediated cytokine signaling to prevent immunodeficiency." (PMID 29304122, 2018). "However, inactivation of TYK2 by a mutation leading to early termination of TYK2 mRNA expression and several JAK3 inactivating amino acid substitutions have been linked to immunodeficiency and SCID." (PMID 27713259, 2010). "With this consideration, we have noted the presence of rare variants in other immunodeficiency genes (JAK2, JAK3, IL17RA, IL12RB2, CARD14, and TYK2) in our various patients, which could feasibly contribute to the penetrance and/or differences in the clinical phenotypes of the patients." (PMID 36672844, 2022). "Such an allelic series provides a natural genetic “dose-response curve”, suggesting that reducing the activity, but not complete inactivation of TYK2, may be an opportunity for intervention in immune diseases." (PMID 33293539, 2020).
type 1 diabetes (27 papers, 2015 to 2026). "In conclusion, our results provide genetic evidence that IL-2, IL-6 and TYK2 signalling are associated with type 1 diabetes risk." (PMID 39271518, 2024). "We did not observe such robust evidence for co-localisation between IL2RA, IL6R, IL6ST or TYK2 eQTL and the risk of type 1 diabetes in other cell types or in spleen or pancreas." (PMID 39271518, 2024). "Using missense variants, genetically proxied TYK2 (encoding tyrosine kinase 2) expression levels were associated with type 1 diabetes risk (OR 0.61 [95% CI 0.54, 0.69])." (PMID 39271518, 2024). "Whole-blood TYK2 expression and the risk of type 1 diabetes did not co-localise, whereas when using the missense mutation rs2304256 in TYK2 as an instrument in Mendelian randomisation, TYK2 expression was associated with type 1 diabetes risk." (PMID 39271518, 2024). "Previous studies found an association of TYK2 candidate with type 1 diabetes mellitus and a role of TYK2 in regulating apoptotic and pro-inflammatory pathways in pancreatic β-cells through modulation of the type I interferon signaling pathway." (PMID 38674089, 2024). "Overall, our TYK2 findings are consistent with previous studies suggesting that TYK2 signalling is associated with the risk of type 1 diabetes." (PMID 39271518, 2024). "GWAS studies have identified polymorphisms in the coding sequence of TYK2 which modify type 1 diabetes risk." (PMID 37867531, 2023). "Lately, attention has focused on TYK2, a candidate gene for type 1 diabetes whose genetic variants that decrease TYK2 activity are associated with protection against the disease." (PMID 37854597, 2023). "To study which specific blood immune cells or tissues mediate the association between IL2RA, IL6R, IL6ST and TYK2 expression and type 1 diabetes risk, we analysed their pairwise co-localisation with type 1 diabetes risk in spleen, pancreas and subsets of blood immune cells." (PMID 39271518, 2024). "Furthermore, we identified a significant co-localization with GWAS signals in a SNP (rs2304256) for the TYK2 gene, which was associated with multiple traits, including type 1 diabetes mellitus, SLE, primary biliary cirrhosis, and psoriatic arthritis." (PMID 39288763, 2024). "In addition, the investigation of functional missense variants suggested that TYK2 signalling is involved in the aetiology of type 1 diabetes." (PMID 39271518, 2024). "The TYK2 gene is associated with development of type 1 diabetes." (PMID 36289205, 2022). "Moreover, we investigated the role of genetic polymorphism of the TYK2 gene in patients with type 1 diabetes including those with flu-like symptoms at the onset of diabetes." (PMID 33799705, 2021). "Here, we elucidated that the tyrosine kinase 2 (Tyk2) gene, encoding an interferon receptor signaling molecule, is responsible for virus-induced diabetes in mice, and its promoter variant confers a risk of type 1 diabetes in humans." (PMID 33799705, 2021). "Our findings support the targeting of IL-2, IL-6 and TYK2 signalling in prevention of type 1 diabetes." (PMID 39271518, 2024). "We focused on this TYK2 inhibitor for two reasons: first, due to TYK2 importance for type 1 diabetes pathogenesis." (PMID 37854597, 2023). "There were two hits prioritized by SuSiE analysis shared between TYK2 expression and above outcomes in several tissues, and additionally type 1 diabetes in visceral adipose and lung." (PMID 36842216, 2023). "In addition, a previous human genome-wide study suggested the type 1 diabetes (T1D) susceptibility region to be 19p13, where the human TYK2 gene is located (19p13.2)." (PMID 26288847, 2015). "The specificity toward the TYK2 pseudokinase domain may offer a favorable safety profile, underscoring the therapeutic potential of pseudokinase-targeted strategies in type 1 diabetes and other autoimmune conditions." (PMID 40534861, 2025).
type 1 diabetes (continued). "Furthermore, our Mendelian randomisation estimates represent the influence of small changes in IL2RA, IL6R and TYK2 expression during the entire life course before the diagnosis of type 1 diabetes." (PMID 39271518, 2024). "Thus, natural history studies and clinical prevention trials should pinpoint the optimal stage of pathogenesis at which to interfere with IL-2, IL-6 or TYK2 signalling to prevent type 1 diabetes." (PMID 39271518, 2024). "Conversely, our findings, along with others, provide further preclinical evidence that TYK2 inhibitors could be considered a strategy for an early therapy for type 1 diabetes." (PMID 37854597, 2023). "Our present findings add to the existing evidence that TYK2 inhibition may be an efficient treatment strategy for type 1 diabetes." (PMID 37854597, 2023). "As TYK2 inhibition has raised as a potential therapeutic target for the prevention or treatment of type 1 diabetes, we investigated whether the selective TYK2 inhibitor deucravacitinib could protect β-cells from the effects of IFNα and other proinflammatory cytokines (i.e., IFNγ and IL-1β)." (PMID 37854597, 2023). "As these findings place TYK2 as a critical regulator of the type I IFN signaling pathway in β-cells, selective TYK2 inhibition has emerged as a drug target to treat type 1 diabetes." (PMID 37854597, 2023). "Interestingly, a recent integrative analysis of genetic association, functional genomics data and protein–protein networks identified DGKQ as a potential novel type 1 diabetes therapeutic gene target along with other novel and known targets, e.g., IL2RA, IL6ST, IL6R and TYK2." (PMID 35142878, 2022). "However, the role of TYK2 in CD8+ T cells and autoimmune type 1 diabetes (T1D) is poorly understood." (PMID 38351043, 2024).
Autoimmunity (26 papers, 2014 to 2026). The occurrence of an immune reaction against the organism's own cells or tissues. "Our results explain why paradoxically, the TYK2:p.Pro1104Ala variant, in the context of its conferred protection against autoimmunity, is at the same time associated with an increased level of lymphocytes." (PMID 39835539, 2025). "TYK2 missense mutations protect against type 1 diabetes (T1D), and inhibition of TYK2 shows promise in other autoimmune conditions." (PMID 40335415, 2025). "In attempting to understand the complex yin and yang of predisposition to infectious disease and protection from autoimmunity of the TYK2:p.Pro1104Ala variant, our study is a first step toward understanding of cellular mechanisms regulated by this variant." (PMID 39835539, 2025). "For the first time, we describe that the TYK2:p.Pro1104Ala general autoimmunity protective variant exerts its function through effects on multiple immune cell subpopulations at a human, general population level." (PMID 39835539, 2025). "In this regard, the TYK2:p.Pro1104Ala loss‐of‐function variant has been associated with protection against autoimmunity." (PMID 39835539, 2025). "In particular, loss of function mutations and inhibition of TYK2 suppress autoimmunity in mice and humans." (PMID 39835539, 2025). "Our work links the cellular mechanism regulated by the TYK2:p.Pro1104Ala variant to autoimmunity protection and supports TYK2 as a therapeutic target in autoimmunity." (PMID 39835539, 2025). "Missense mutations in TYK2 are associated with protection against type 1 diabetes (T1D), and inhibition of TYK2 shows promise in the management of other autoimmune conditions." (PMID 38766166, 2024). "Considering the Janus family of kinases (JAKs), activation of JAK/STAT signals through JAK mutations or abnormal TYK2 signals constituted by JAK is crucial for inducing autoimmunity and some immune deficiency syndromes." (PMID 35937845, 2022). "This led to the theory that TYK2 function constitutes a spectrum, with complete abrogation causing immunodeficiency and augmented function increasing susceptibility to autoimmunity." (PMID 32477401, 2020). "It is thus suggested that the risk for diabetes conferred by the TYK2 promoter variant is distinct from autoimmunity against pancreatic β-cells." (PMID 26288847, 2015). "The autoimmunity-associated TYK2 variants TYK2I684S and TYK2P1104A can rescue signaling defects via their association with other intact JAKs." (PMID 24833526, 2014). "Our work underlines the current utility of TYK2 as a therapeutic target in autoimmunity." (PMID 39835539, 2025). "Our work identifies the cellular mechanisms of regulation by the TYK2:p.Pro1104Ala variant providing novel hypotheses for the general immune mechanisms of protection from autoimmunity." (PMID 39835539, 2025). "Several TYK2 variants have been associated with autoimmunity and are generally protective." (PMID 39835539, 2025). "Using an established partial loss‐of‐function variant to mimic therapeutic TYK2 inhibition, we show that potential protection from autoimmunity mediated by TYK2 inhibition may be counteracted by an increased risk of lung cancer and non‐Hodgkin lymphoma." (PMID 35747941, 2022). "Interestingly, the method was able to identify rs34536443, a well-characterised non-synonymous variant in autoimmunity, as the likely causal variant for TYK2 locus with a PIP of 80%." (PMID 33106285, 2021). "Together, these findings demonstrate that DMS can prospectively reveal novel druggable sites, clarify structure-activity relationships (SAR), and highlight TYK2 degradation as a potential therapeutic strategy in autoimmunity." (PMID 42268925, 2026). "The application of JAK and TYK2 inhibitors in other autoimmune conditions suggests chronic dosing would likely be necessary." (PMID 38766166, 2024).
Autoimmunity (continued). "While IEI have been thought to be rare, common single‐nucleotide polymorphisms (SNPs) have also been found in TYK2 and IFNAR1 and are associated with improved protection from infection as well as increased risk of autoimmunity." (PMID 36929731, 2023). "Recent data demonstrate that inactivating the catalytic activity of TYK2 with novel small molecules can attenuate autoimmunity." (PMID 24833526, 2014). "Additionally, for first time we show that TYK2:p.Pro1104Ala variant increases the regulatory CD4+ T cells, in line with the protective function of this variant in autoimmunity." (PMID 39835539, 2025). "This is consistent with TYK2 partial loss of function mutations known to be protective against autoimmunity without evidence of susceptibility to infection." (PMID 39403378, 2024). "That is, TYK2 may play a role in autoimmunity and inflammation through abnormal expression in JAK-STAT pathway, thus leading to JIA." (PMID 36362342, 2022). "Tyrosine kinase 2 (TYK2) is another key regulator of type I and type III IFN signalling, and gene variants predicted to decrease TYK2 functionality are associated with a reduced risk of T1D and other autoimmune conditions." (PMID 32942706, 2020). "One of the other largest effects of TYK2:p.Pro1104Ala mutation on immune cell levels was an increase in the absolute count of B cells, most notably the IgD+CD24− mature naïve B cells population increased, confirming the protective effect of naïve cells on autoimmunity." (PMID 39835539, 2025). "These timepoints were appropriate for our study; however, it will be informative to determine the impact of TYK2 inhibition during longer periods of follow-up, as the application of JAK and TYK2 inhibitors in other autoimmune conditions suggests chronic dosing would likely be necessary." (PMID 40335415, 2025). "Effective in TYK2-driven inflammation; potential relevance to IFN-driven autoimmunity." (PMID 41153754, 2025). "Pathway crosstalk analysis for potential therapeutic intervention identified a network of 53 interconnecting genes, including genes that are already therapeutic targets in AS and other autoimmune conditions, such as JAK1 and TYK2, alongside yet unexplored genes." (PMID 37388915, 2023). "These inhibitors specifically target γc chain receptor signaling while sparing the signaling pathways of immunoregulatory cytokines, such as IL-10R (TYK2/JAK1), IL-27R (JAK1/JAK2), and IL-35R (JAK1/JAK2), which may contribute to preventing autoimmunity in the hair follicle." (PMID 41488086, 2025). "Thus, the immune milieu created by the TYK2:p.Pro1104Ala variant is not completely unrelated to a proper immune response and we suggest that the shift in memory helper T cells may have a role in protection from autoimmunity, but this observation requires replication in independent studies." (PMID 39835539, 2025).